RNU6-562P (RNA, U6 small nuclear 562, pseudogene)
Gene: Small nuclear RNA gene on chromosome X (75,202,703 to 75,202,809, forward strand). Ensembl gene ENSG00000199601.
Homologues: Orthologues: chimpanzee U6 (100% identical). Paralogues in human: RNU6-1152P (92% identical), RNU6-41P (92% identical), RNU6-820P (92% identical), RNU6-15P (91% identical), RNU6-393P (91% identical), RNU6-45P (91% identical), RNU6-1019P (90% identical), RNU6-1060P (90% identical), RNU6-12P (90% identical), RNU6-13P (90% identical), RNU6-166P (90% identical), RNU6-16P (90% identical), and 1284 more.